CDCA7L (cell division cycle associated 7 like)
Description:
Plays a role in transcriptional regulation as a repressor that inhibits monoamine oxidase A (MAOA) activity and gene expression by binding to the promoter. Plays an important oncogenic role in mediating the full transforming effect of MYC in medulloblastoma cells. Involved in apoptotic signaling pathways; May act downstream of P38-kinase and BCL-2, but upstream of CASP3/caspase-3 as well as CCND1/cyclin D1 and E2F1.
Synonyms: JPO2; R1; RAM2
Tractability: PROTAC: UniProt records ubiquitination sites on it; ubiquitination databases record sites on it.
Gene: Protein-coding gene on chromosome 7 (21,899,974 to 21,946,219, reverse strand). Ensembl gene ENSG00000164649.
Subcellular location: Cytoplasm; Nucleus
Subcellular location (Human Protein Atlas): Nucleoli; Nucleoplasm; Cytosol; Nucleoli fibrillar center
Gene Ontology:
Molecular function: protein binding
Biological process: positive regulation of cell population proliferation; regulation of DNA-templated transcription
Cellular component: cytosol; fibrillar center; nucleolus; nucleoplasm; nucleus; cytoplasm
Genetic constraint (gnomAD): Loss-of-function variants: 45 observed, 58.71 expected, observed/expected ratio (o/e) 0.77, 90% interval 0.6 to 0.98. The upper end of that interval is the gene's LOEUF score, 0.98, which puts it in group 4 of 6, group 1 being the genes least tolerant of losing a copy. Missense variants: 644 observed, 598.03 expected, observed/expected ratio (o/e) 1.08, 90% interval 1.01 to 1.15. Synonymous variants: 236 observed, 213.34 expected, observed/expected ratio (o/e) 1.11, 90% interval 0.99 to 1.23.
Homologues: Orthologues: chimpanzee CDCA7L (99% identical), dog CDCA7L (88% identical), macaque CDCA7L (87% identical), pig CDCA7L (87% identical), guinea pig CDCA7L (87% identical), mouse Cdca7l (77% identical), rat Cdca7l (76% identical), rabbit CDCA7L (72% identical), tropical clawed frog cdca7l (46% identical), zebrafish cdca7b (38% identical). Paralogues in human: CDCA7 (39% identical).
Diseases named in the same sentence as CDCA7L in open-access papers:
CDCA7L is named in the same sentence as 41 diseases in open-access papers, as found by Europe PMC text mining. Sharing a sentence is not in itself a finding about the gene and the disease. The quoted sentences say what the papers report.
medulloblastoma (6 papers, 2009 to 2024). A malignant, invasive embryonal neoplasm arising from the cerebellum. "The elevated expression of CDCA7L in medulloblastoma cells and its ability to enhance c-Myc-mediated transformation further implicate it in neoplastic processes, highlighting its role in cancer progression." (PMID 39796114, 2024). "We found a decrease in Cdca7l gene expression, a transcription factor involved in cell apoptosis and medulloblastoma transformation." (PMID 19331679, 2009). "Similarly, CDCA7L is overexpressed in several cancers, where it promotes cellular proliferation, particularly in medulloblastoma cells." (PMID 39796114, 2024). "CDCA7L interacts with c-Myc in bringing about cellular transformation in medulloblastoma." (PMID 27829003, 2016).
multiple myeloma (5 papers, 2012 to 2020). "Interestingly, previous research has shown that the risk allele of the genetic variant most highly associated with multiple myeloma (rs4487645) was associated with increased CDCA7L expression." (PMID 32859263, 2020). "If the risk variant indeed exerts its pathogenic effect through an effect on CDCA7L expression, CDCA7L’s effects on DNA methylation might be involved in the pathogenesis of multiple myeloma." (PMID 32859263, 2020). "For example, in the GSE9782 trial, myeloma patients (n = 265 total) in the top quartile of CDCA7L expression (measured in bone marrow plasma cells) exhibited significantly shorter overall survival than patients in the bottom quartile [p = 3.1 × 10-4; hazard ratio (HR) = 2.3]." (PMID 31139207, 2019). "Moreover, our multi-SNP GI was a stronger predictor of CDCA7L expression (F = 171) as compared with rs4487645 (F = 60) and may therefore be useful in gaining more insight into the role of CDCA7L in multiple myeloma." (PMID 32859263, 2020).
melanoma (3 papers, 2012 to 2025). A malignant, usually aggressive tumor composed of atypical, neoplastic melanocytes. "We first examined if CDCA7L repression in melanoma cell lines was associated with DNA hypermethylation within its promoter." (PMID 26504497, 2015). "For one of the ICCG genes (CDCA7L), we found that its down-regulation in melanoma cells was associated with deposition of repressive chromatin marks, including H3K27me3." (PMID 26504497, 2015). "Altogether, these results support the hypothesis that permanent repression of CDCA7L in melanoma cells is linked to progressive deposition of repressive epigenetic marks within the gene promoter." (PMID 26504497, 2015). "With the exception of CDCA7L, affected mitosis/division-related genes displayed, however, only partial repression in melanoma cells." (PMID 26504497, 2015). "Compared to other ICCG genes, CDCA7L also showed the most extensive level of repression in melanoma cell lines." (PMID 26504497, 2015). "One possible explanation for the persistent repression of CDCA7L in melanoma cells was that DNMT1 depletion led to the irreversible activation of a factor that imposes silencing of the gene." (PMID 26504497, 2015). "This construct was stably transfected into two melanoma cell lines that express CDCA7L (Mi665/2 and SK-MEL-23) and two melanoma cell lines that show silencing of the gene (MZ2-MEL3.1 and BB74-MEL)." (PMID 26504497, 2015). "To address this issue, we focused our studies on CDCA7L because repression of this ICCG gene was most significantly correlated with CG gene activation in melanoma tissues." (PMID 26504497, 2015). "This was confirmed by RT-qPCR experiments showing that whereas CDCA7L is expressed in melanocytes, it is almost completely silenced in several melanoma cell lines." (PMID 26504497, 2015). "We reasoned that if CDCA7L repression is linked to the presence of a silencing factor, the promoter of the gene would show reduced activity in non-expressing melanoma cell lines." (PMID 26504497, 2015). "Another possible explanation for the permanent repression of CDCA7L in melanoma cells was that down-regulation of this gene during the phase of DNMT1 depletion allowed local deposition of repressive epigenetic marks, which progressively locked the gene into an irreversible silent state." (PMID 26504497, 2015). "To study this possibility, we decided to evaluate the activity of the CDCA7L promoter in melanoma cell lines that either do or do not express the gene." (PMID 26504497, 2015).
atherosclerosis (1 paper, 2021). A disease characterized by the build-up of fatty material and calcium deposition in the arterial wall resulting in partial or complete occlusion of the arterial lumen. "Whether the rest of them, including Dkk2, Ltbp2, Lamb1, Cdca7l, Dclk1, and Slc45a4, are associated with atherosclerosis and d-flow has not been reported." (PMID 34282126, 2021).
glioma (1 paper, 2022). A benign or malignant brain and spinal cord tumor that arises from glial cells (astrocytes, oligodendrocytes, ependymal cells). "For example, Cdca7l promotes the proliferation and infiltration of glioma cells." (PMID 35474103, 2022).
hepatitis B (1 paper, 2024). "Furthermore, we explored public GWAS databases containing data on HBV recurrence after LT in HBsAg-positive hepatitis B patients, recruited in other ethnic populations, to validate the SNP markers located on RGL1, CDCA7L, and AQP9 genes identified in the entire cohort." (PMID 39796114, 2024).
hepatocellular carcinoma (1 paper, 2024). A malignant tumor that arises from hepatocytes. "Overexpression of CDCA7L was found to promote hepatocellular carcinoma cell proliferation and colony formation, whereas knocking down CDCA7L inhibited these processes." (PMID 39796114, 2024).
Pancytopenia (1 paper, 2017). An abnormal reduction in numbers of all blood cell types (red blood cells, white blood cells, and platelets). "Most of the genes from day 1 appeared 2-fold downregulated (e.g., CDCA7L or GBP2), but three were 3–5-fold upregulated (C11orf96, GLUL, TM4SF19) relative to H0 when developing a HARS without pancytopenia." (PMID 28236054, 2017).
plasma cell neoplasm (1 paper, 2025). A clonal proliferation of immunoglobulin-secreting plasma cells. "Given that MYC dysregulation is a hallmark of plasma cell neoplasms, CDCA7L emerges as a strong candidate for the functional basis of the rs4487645 association." (PMID 40244254, 2025).
rheumatoid arthritis (1 paper, 2024). A chronic, systemic autoimmune disorder characterized by inflammation in the synovial membranes and articular surfaces. "Its annotated gene, CDCA7L, further supports this association with its links to both rheumatoid arthritis and aging." (PMID 38365790, 2024).
infection (12 papers, 2010 to 2025). The state of being infected such as from the introduction of a foreign agent such as serum, vaccine, antigenic substance or organism. "Notably, genes such as Cyp26b1, Dbp, Kcng1, Cdca7l, Paxip1, Stxbp2 and Gpi1 were also observed to be significantly up-regulated (p<0.05) in the hMHC mice on various days post-infection." (PMID 40822594, 2025).
cancer (7 papers, 2012 to 2024). A tumor composed of atypical neoplastic, often pleomorphic cells that invade other tissues. "In these cancers, several biomarkers have been described as predicting therapeutic outcomes, e.g., CDCA7L, BICD1, DDX17, S1PR1 and SEPT7." (PMID 33260776, 2020). "CDCA7L has been shown to be oncogenic in several cancers, in which MYC physically interacts and induces expression of CDCA7L (refs 8, 9)." (PMID 27882933, 2016). "The nine mRNAs are coding for proteins involved in cell cycle regulation (CDCA7L), modification of the T cell and B cell immune response (GBP2, GLUL, HERC5, PPP3CC), erythropoiesis (GBP2), and cell migration of cancer and hematopoietic cells (HERC5, HMHA1)." (PMID 28236054, 2017).
tumor (5 papers, 2012 to 2024). "In vivo studies using nude mouse models have shown that CDCA7L overexpression significantly accelerates tumor growth." (PMID 39796114, 2024). "Conversely, silencing CDCA7L expression suppressed cell proliferation and colony formation and significantly reduced tumor burden in YY-8103 and MHCC-97H HCC cells." (PMID 39796114, 2024). "The importance of enhancer-mediated CDCA7L expression in MM demonstrates the potential of translating basic mechanistic insights of tumour initiation towards development of therapeutic strategies." (PMID 27882933, 2016).
CDCA7L also shares sentences with these, for which no sentence is quoted: viral infection (6 papers); Allergy (2); breast carcinoma (2); rhabdomyosarcoma (2); airway hyperresponsiveness (1); allergic rhinitis (1); anaphylaxis (1); autism spectrum disorder (1); cardiomyopathies (1); cervical cancer (1); colon cancer (1); COVID-19 (1); Duchenne muscular dystrophy (1); glioblastoma (1); HIV-1 infection (1); ICF syndrome (1); kidney cancer (1); leukemia (1); liver cancer (1); lung carcinoma (1); lung disease (1); Obesity (1); ovarian carcinoma (1); pancreatic cancer (1); prostate carcinoma (1); renal carcinoma (1); Rett syndrome (1); worm infection (1).